IL6 (interleukin 6)
Diseases named in the same sentence as IL6 in open-access papers (continued):
Sharing a sentence is not in itself a finding about the gene and the disease.
breast cancer (continued). "This study demonstrates that IL6 signaling promotes aggressiveness in luminal breast cancer cells making them more basal-like." (PMID 26173622, 2015). "Surprisingly, C57BL/6 BMDMs cultured with 4T1 mouse mammary carcinoma-conditioned medium exhibited a 2–3 fold increase in the production of TNFα, IL-6, and CCL2 in the presence of LPS." (PMID 26177198, 2015). "Table-V shows that the mean serum levels of both TPA and IL-6 were significantly higher in patients with ductal type of breast cancer than those with lobular type in both breast cancer groups." (PMID 25225536, 2014). "It has been show that PGE2 in combination with IL-6 secreted by tumor-derived fibroblast can increase the incidence of stem-like cells in breast cancer cells." (PMID 25343626, 2014). "Particularly, IL-6 as a poor prognostic factor in breast cancer patients progresses cancer metastasis." (PMID 24976685, 2014). "Tat can up-regulate cytokines (i.e., IL-6, IL-8) expression in breast cancer cells, and can also increase the expression of the chemokine CCL5 in astrocytes." (PMID 26784879, 2014). "Benzyl isothiocyanate, an extract from cruciferous vegetables, blocks STAT3 activation induced by IL-6 in MDA-MB-453 breast cancer cells and PANC-1 pancreatic cancer cells." (PMID 24743778, 2014). "Immunoblotting analysis provided a link between ezrin expression and a key angio/lymphangiogenesis signaling pathway by revealing that ezrin regulates Stat3 activation, VEGF-A/-C and IL-6 expression in breast cancer cell lines." (PMID 25231728, 2014). "This study was carried out to determine the potential utility of CTGF and IL6 concentrations in blood for evaluation of radiation fibrosis in a population of breast cancer patients with prospective clinical scores of fibrosis." (PMID 24885397, 2014). "In this regard, many clinical studies have shown that high serum levels of IL-8 and IL-6 correlate with poor prognosis in breast cancer patients." (PMID 25136593, 2014). "Recently, IDO was demonstrated to drive IL-6 production in mice with lung cancer and breast cancer metastasis, while IL-6 in turn was reported to induce IDO expression via JAK/STAT signaling in rat hippocampus." (PMID 24657910, 2014). "We performed the Wechsler Memory Scale-Revised (WMS-R) and measured plasma IL-6 levels for 105 breast cancer surgical patients within 1 year after the initial therapy." (PMID 24756915, 2014). "The IL-6/JAK2/STAT3 pathway was found to be active in CD44+/CD24− breast cancer cells, and inhibitors blocking this pathway suppressed growth of xenograft tumors." (PMID 24743778, 2014). "Among ER+ breast cancer patients, BMI, leptin and IL-6 significantly correlated with T status and presence of distant metastases (M+)." (PMID 25338520, 2014). "Both TPA and IL-6 are highly sensitive in detecting breast cancer and the combination of the two tumor markers will increase the specificity for detecting breast cancer up to 96.7%." (PMID 25225536, 2014). "The present study investigated the impact of IL6 genotype on early events and treatment response in an ongoing cohort of breast cancer patients." (PMID 25305747, 2014). "In this study, we show that in comparison with ‘young’ MSCs, senescent human umbilical cord mesenchymal stem cells (s-UCMSCs) significantly promote the proliferation and migration of breast cancer cells through the IL-6/STAT-3-dependent pathway." (PMID 25419563, 2014). "Noticeably, among those cytokines GRO-alpha and IL6 were produced at detectable levels even by primary breast cancer cells alone (KBr)." (PMID 24327602, 2014). "Recently, another inflammatory cytokine IL-6 has been reported as a potent inducer of EMT in breast cancer cells with an epithelial phenotype." (PMID 24789104, 2014). "Other studies show high levels of IL6 in serum of breast cancers appear to be related to poor prognosis, possibly involved in epithelial-to-mesenchymal transition." (PMID 25100201, 2014).
breast cancer (continued). "In the diagnosis of breast cancer, the TPA test had a greater diagnostic sensitivity (96.7%) in detecting breast cancer compared to that of IL-6 test (87.8%) (Table-VI)." (PMID 25225536, 2014). "LPS triggered increased expression of TLR4 downstream signaling pathway protein myeloid differentiation factor 88(MyD88) and resulted in interleukin (IL)-6 and IL-10 higher production by human breast cancer cells." (PMID 25299052, 2014). "Elevated levels of IL-6 correlate with poor prognosis for a number of types of cancer, such as breast cancer and lung cancer." (PMID 24789104, 2014). "A number of studies have shown that CAAs support and expedite breast cancer progression by providing proinflammatory cytokines, such as IL-6, TNF-α, and reactive oxygen species." (PMID 25136593, 2014). "Antidepressant treatment reduced IL-6 levels in depressed patients and increased adherence to adjuvant breast cancer treatment." (PMID 25305747, 2014). "In a recent study, we found that PTEN inactivation in HER2-positive breast cancer cells activates an IL-6, STAT3, AKT and NF-κB involved inflammatory feedback loop, which expands EMT type of breast CSCs." (PMID 26932376, 2014). "In this study, a significant high serum level of IL-6 was detected in breast cancer patients compared with healthy control group, with direct association to clinical stages Table-II and IV." (PMID 25225536, 2014). "Cytokines, such as SDF-1, support proliferation and migration of breast cancer cells expressing CXCR4 receptor, as well as high serum levels of Interleukin-6 and Interleukin-8 are associated with poor outcome in breast cancer patients." (PMID 24327602, 2014). "Reactive oxygen species levels were positively correlated with BMI, leptin and IL-6 in ER+ breast cancer patients." (PMID 25338520, 2014). "We have described previously in the context of bone metastasis induced by breast cancer cells that LPA through LPA1 controls the expression of IL6, IL-8, CSF2(GM-CSF), and CXCL1(Groα)." (PMID 24828490, 2014). "The serum level of TPA and IL-6 in both breast cancer patients groups were compared to their values in another 30 healthy women age ranged between 28-65 years and considered as a healthy control group." (PMID 25225536, 2014). "The role of IL-6 and IL-8 in the self-renewal of breast cancer stem cells has been extensively studied." (PMID 24762066, 2014). "Table-II demonstrates that the mean serum levels of both TPA and IL-6 were significantly higher in breast cancer patients than healthy control group." (PMID 25225536, 2014). "ASCs produced SDF-1, PDGF-D, IL-6 and IL-8 that contributed to growth and invasion/metastasis of breast cancer cells in vitro and in vivo." (PMID 24586900, 2014). "Chemotherapy has been shown to increase IL-6 levels in breast cancer patients and to activate NF-κβ." (PMID 25305747, 2014). "In particular, the aberrant production of IL-6 and CCL2 in mammary cancer activates STAT3 in CAFs, which finally sustains tumor-associated inflammation and is required for breast cancer cell migration." (PMID 25136593, 2014). "Among the adipokines, an emerging central role in the breast cancer pathogenesis and prognosis has been recently attributed to the inflammatory mediators TNFα and IL-6." (PMID 23819063, 2013). "Using a murine breast cancer cell model, we showed that murine breast cancer cells with high IL-6 expression recruited more MDSCs and that the metastasizing capacity of cancer cells paralleled MDSC recruitment in tumor-bearing mice." (PMID 24021059, 2013). "In the past two years, evidence has emerged that an epigenetic switch occurs during breast cancer transformation in which inflammatory circuits involving IL6 and IL8 mediate self-renewal of CICs." (PMID 23935876, 2013). "In breast cancer patients, serum Il-6 levels correlate with the presence of metastasis and disease prognosis." (PMID 23520493, 2013).
breast cancer (continued). "A recent study demonstrated activation of the IL-6/Jak/Stat pathway in basal-like breast cancer cells in vitro and in vivo." (PMID 23520493, 2013). "Recent study showed that IL-6 had the ability to induce CD44 positive cancer stem cells in breast cancer oncogenesis model." (PMID 23593346, 2013). "We recently reported that in Th1 cytokine enriched microenvironment, MIG/CXCL9 and IP-10/CXCL10 were upregulated while IL-1β and IL-6 were downregulated with concomitant reduction in the percentage of MDSC in a 3D breast cancer model." (PMID 23394575, 2013). "In breast cancer serum IL-6 levels were significantly higher than in a control group of healthy women." (PMID 23864954, 2013). "Studies have also found that ulinastatin enhances the inhibitory effect of docetaxel in breast cancer by a mechanism consistent with the down-regulated expression of IL-6, IL-8, and TNF-α." (PMID 23575450, 2013). "There is also evidence to suggest that breast cancer cells cultured as 3-D spheroids express a higher level of IL-6 mRNA." (PMID 23372803, 2013). "It has been shown that fibroblasts derived from metastatic breast cancers have IL-6 dependent growth and invasion." (PMID 23840733, 2013). "In the models of breast cancer, head and neck cancer and lung cancer, IL-6 also serves as an inducer of EMT." (PMID 23977098, 2013). "MDSC-derived IL-6 and sIL-6Rα induced persistent activation of STAT3 and increased invasiveness of breast cancer cells via an IL-6 trans-signaling mechanism." (PMID 24021059, 2013). "We found that murine breast cancer cells with high IL-6 expression recruited more MDSCs and that the metastasizing capacity of cancer cells paralleled MDSC recruitment in tumor-bearing mice." (PMID 24021059, 2013). "In breast cancer, receptor gp130 mediates IL-6 signals; inhibiting IL-6 signaling and production in turn inhibits in vitro activation of STAT3 as well as in vivo tumor cell proliferation and number of metastases." (PMID 23710200, 2013). "Several reports indicate that high IL-6 serum levels in patients with breast carcinoma indicate a poor prognosis due to correlation with metastases in patients with untreated breast cancer." (PMID 23552194, 2013). "In this study, we showed that IL-6 derived from metastasizing murine breast cancer cells recruited MDSCs and tumor-expanded MDSCs expressed Adam-family proteases, which facilitated shedding of IL-6 receptors, thereby providing sIL-6Rα." (PMID 24021059, 2013). "Our thesis is further supported by observations made in lung and breast cancer patients where secreted IL-6 triggered its own production." (PMID 24155968, 2013). "In the epithelial-like T47D breast cancer cells, IL6-induced EMT generated CD44+ cells with stem-like properties." (PMID 23776679, 2013). "In order to validate the Fluidigm data, we focused our attention on the pivotal breast cancer stem cells growth factor Interleukin 6 (IL6)." (PMID 24260469, 2013). "In this study, we focused on IL-6 and TNF-α due to their association with poor prognosis for breast cancer patients." (PMID 23372803, 2013). "Adjuvant treatment of women with breast cancer with paclitaxel, enhanced serum levels of IL-6, IL-8 and IL-10." (PMID 23320561, 2013). "Intrinsic production of IL-6 in the ER(+) breast cancer cell lines MCF-7, T47D, ZR-75-1, and SK-BR promotes cell death in response to drugs, inducing morphological changes, and apoptosis with DNA fragmentation." (PMID 23552194, 2013). "IL-6 is a master regulator of inflammation and correlates with poor outcome and survival in breast cancer." (PMID 23840733, 2013). "Metformin has been shown to target Stat3 and induce apoptosis in triple-negative breast cancers as well as significantly decrease serum IL-6 level in breast cancer patients." (PMID 23372803, 2013). "An IL-6/Jak/Stat gene signature predicted higher rates of metastasis formation in breast cancer patients." (PMID 23520493, 2013).
breast cancer (continued). "This potential tumor-MDSC axis involving IL-6 trans-signaling directly affected breast cancer cell aggressiveness, leading to spontaneous metastasis." (PMID 24021059, 2013). "The enhanced IL-6 signaling mediated by the cancer cell-MDSC interaction augmented 4T1 breast cancer cell aggressiveness." (PMID 24021059, 2013). "Specifically, breast cancer stem cells are modulated by signal transduction pathways including the Wnt and IL-6/JAK2/STAT3 pathway." (PMID 24392029, 2013). "We have previously demonstrated in our cross-sectional study that inflammatory biomarkers known to be elevated in breast cancer patients (IL-6 and CRP) are also increased in obese and insulin resistant pre-menopausal women." (PMID 23374911, 2013). "This is consistent with recent results demonstrating that the cytokine IL-6 is able to stimulate breast cancer stem cells and JAK2/STAT3 signaling pathway is required for growth of breast cancer stem cells." (PMID 24376586, 2013). "Other important parameters are cytokines, such as interleukin-6 (IL-6) and interleukin-8 (IL-8), which independently show correlations with breast cancer disease stage and progression." (PMID 24088535, 2013). "A previous study has shown that IL-6 can induce the EMT phenotype in human breast cancer epithelial-like cell lines." (PMID 22134360, 2012). "Recently, the inflammatory cytokine IL-6 has been reported as a potent inducer of epithelial-mesenchymal transition (EMT) in breast cancer cells with an epithelial phenotype." (PMID 22134360, 2012). "Herein, we provide evidence that IL-6 is capable of generating CD44+ cells with stem-like properties through induction of the EMT in the epithelial-like T47D breast cancer cells." (PMID 22134360, 2012). "It has also been shown that IL-6 treatment promotes the formation of mammosphreres of human breast cancer and normal mammary gland epithelial cells, consistent with the activation of Notch signaling." (PMID 22952749, 2012). "IL-6 levels in breast cancer patients have been found to correlate with the clinical stage of the disease as well as with the rate of recurrence." (PMID 22235336, 2012). "IL-6 has been described to be involved in the stress response induced by the invasion of an osteoblastic matrix by breast cancer cells." (PMID 22235336, 2012). "High IL-6 serum levels in breast cancer patients have been identified as an unfavorable prognostic indicator." (PMID 22235336, 2012). "In breast cancer, tumor tissue exhibits high expression levels of IL-6 compared with matched normal breast tissue samples, which also correlate with more advanced tumor grades." (PMID 22134360, 2012). "In the cross-species xenograft model for breast cancer utilized in this experiment, mouse cytokines can activate human receptors with the exception of IL-6." (PMID 22315691, 2012). "Recent studies have indicated that IL-6 is capable of inducing an epithelial-mesenchymal transition (EMT) phenotype in human breast cancer cells." (PMID 22134360, 2012). "The “IL-6 gene signature” also segregated the breast carcinomas of the NKI dataset in two groups, allowing the analysis of prognostic relevance." (PMID 22235336, 2012). "We also established IL-6-knocked-down breast cancer cells (shIL-6_MB231) by using the shIL-6 vector." (PMID 21967801, 2011). "In conclusion, combined high expression of TG2 and IL-6 was related to a poor DMFS outcome in breast cancer." (PMID 21967801, 2011). "Autocrine IL-6 production, a principal mediator of Stat3 activation in breast tumors, was found to be elevated in human mammary cancer/stem cells." (PMID 22140473, 2011). "IL-6 on the other hand is an autocrine and paracrine growth factor for several cancers, including breast cancer and both IL-17 and IL-6 stimulates cancer cell growth and contributes to recurrence and metastasis in breast cancer." (PMID 21859454, 2011).
breast cancer (continued). "One explanation for this observation is that cytokines such as IL-6 which mediate Stat3 activation in breast cancers are expressed at higher levels in lymphatic tissue resulting in increased pStat3." (PMID 22140473, 2011). "Hussein showed that high-levels of IL-6 indicate poor prognosis and the concentration of IL-6 in the serum of breast cancer patients is not only elevated, but increases with the clinical stage of breast cancer." (PMID 21345194, 2011). "Our results suggest that tumor promoting fibroblasts secrete PGE2 and mediate autocrine PGE2 signaling, thereby activating the increased secretion of IL-6, which is required for expansion of breast cancer stem-like cells." (PMID 21957456, 2011). "High serum IL-6 concentration has been reported to be correlated with poor prognosis for breast cancer." (PMID 22023707, 2011). "With highly immunocompromised mice, we evaluated the critical role of TG2 and downstream IL-6 in the distant metastasis of breast cancer cells." (PMID 21967801, 2011). "Taken together, it is evident that both IL-6 and Src signaling through Stat3 is contributing to Jab1 transcription and increased expression in breast cancer." (PMID 21689417, 2011). "Increased serum levels of IL-6 were previously reported in progressive recurrent breast cancer patients, especially in the presence of metastasis, conversely no metastatic cases were enrolled in our cohort." (PMID 22112244, 2011). "Sphere formation decreased markedly both in TG2-knocked-down and IL-6-knocked-down breast cancer cells (shTG2_MB231#1 and shIL-6_MB231#6, respectively) compared with the control empty vector-transfected cells." (PMID 21967801, 2011). "Sasser found that the growth rate of MCF-7 estrogen-receptor-positive (ER+) breast carcinoma cells doubled in vitro and increased even more in vivo following treatment with recombinant human IL-6." (PMID 21345194, 2011). "Dipterinyl calcium pentahydrate (DCP) has previously been shown to inhibit MDA-MB-231 human breast cancer xenographs in nude mice in a manner correlated with increases in plasma IL-12 and IL-4 concentrations, and decreases in plasma IL-6 levels." (PMID 20356392, 2010). "These tumors also over-express Interleukin 6 (IL-6), a pro-inflammatory cytokine that stimulates the growth of breast cancer stem/progenitor cells." (PMID 21092249, 2010). "Our preliminary data also suggested significant increased IL-6 in breast cancer patients compared with hepatitis cancer patients and healthy individuals (P < 0.01) (unpublished data)." (PMID 24281079, 2010). "We showed previously that LPA controls indirectly breast cancer cell-induction of osteoclastogenesis through the secretion of pro-osteoclastic cytokines, IL-6 and IL-8, by tumor cells." (PMID 20305819, 2010). "We have previously observed that IL-6 exposure in breast cancer cells elicits the up-regulation of its own mRNA." (PMID 21092249, 2010). "IL-6/Stat3 signaling has been shown to inhibit E-Cadherin expression in models of prostate and breast cancer." (PMID 20929542, 2010). "Basal-like tumors also over-express the pro-inflammatory cytokine Interleukin-6 (IL-6), a potent growth factor for breast cancer cells that enhances mammospheres growth capacity and malignant features in a paracrine/autocrine fashion." (PMID 21092249, 2010). "For example, the ESR2 and MAPK1 genes in the prostate cancer prediction, and the IL6 and CEBPD in the breast cancer predictions, were associated with several chemicals for each of the diseases." (PMID 20459635, 2010). "We found that pretreatment with FLLL32 but not curcumin (20 μM) was able to inhibit the induction of STAT3 phosphorylation by IL-6 in MDA-MB-453 breast cancer cells, and the effect of FLLL32 was more potent than curcumin." (PMID 20712901, 2010). "IL-6 induces increased motility, cell-cell and cell-substrate dyshesion and epithelial-to-mesenchymal transformation in breast cancer cells." (PMID 24281079, 2010).